DKK3 (dickkopf Wnt signaling pathway inhibitor 3)
Diseases named in the same sentence as DKK3 in open-access papers (continued):
Sharing a sentence is not in itself a finding about the gene and the disease.
glioma (continued). "REIC/Dkk-3 expression was upregulated in Ad-SGE-REIC-transduced glioma cells, and the most prominent effect was obtained after transduction at 10 MOI." (PMID 27625116, 2016). "REIC/Dkk-3 regulates the growth and survival of glioma cells by caspase-dependent and -independent mechanisms via modification of the Wnt signaling pathway." (PMID 27625116, 2016). "Knockdown of miR-92b decreased glioma cell prolifirelation, reduced apoptosis and up-regulated the expression of the target, DKK3, whereas ectopic expression of miR-92b exhibited the opposite effects." (PMID 24325785, 2013). "The present data indicates that miR-92b directly regulate cell proliferation and apoptosis by targeting DKK3 and act as prognostic factors for glioma patients." (PMID 24325785, 2013). "An increase in DKK3 expression could lead to a reduction in the cell survival, proliferation, and invasion of glioma." (PMID 38612910, 2024). "In this study, we showed that the role of the DKK3 gene (Wnt/β-catenin pathway) in grade II or III glioma might be altered in grade IV GBM." (PMID 38672212, 2024). "Interestingly, we found that the expression of DKK3 was the highest in the normal brain tissues, and that its expression decreased as the grade of glioma increased, similar to the results documented in the TCGA database." (PMID 37149563, 2023). "In addition, when evaluating the relationship between DKK3 and memory B cells in all patients with glioma, the LOWESS curve also showed a curvilinear relationship." (PMID 37149563, 2023). "Based on previously published studies and our current findings, we herein present schematic illustrations of the hypothetical role of DKK3 in glioma progression considering its interaction with CTNNB1, FSTL1, and CSNK1A1, which are involved in the Wnt/β-catenin signaling pathway." (PMID 37149563, 2023). "Furthermore, this study indicates that methylation of DKK3 is a rare event in glioma, with no obvious association with the tumor type or grade." (PMID 34064046, 2021). "However, there are few studies investigating the expression of DKK1 and DKK3 in gliomas." (PMID 34064046, 2021). "To test our hypothesis, we analyzed the protein levels of DKK3 and miR-92b in the glioma cells." (PMID 24325785, 2013). "When the patients were divided into grade II or III glioma and GBM groups, a significant positive correlation was found between DKK3 expression and the CD8 + T-cell fraction in the grade II or III glioma group." (PMID 37149563, 2023). "When determining the relationships among DKK3, FSTL1 and CTNNB1, we observed that the higher the grade of glioma was, the stronger the positive correlations between DKK3 and FSTL1 and between DKK3 and CTNNB1." (PMID 37149563, 2023). "We calculated the correlations between the expressions levels of the DKK3, CTNNB1, FSTL1, and CSNK1A1 genes and eight immune cell fractions in grade II or III glioma and GBM." (PMID 37149563, 2023). "We compared DKK3 expression levels in three samples each of the normal human brain, grade II, and grade III gliomas and four samples of grade IV GBM collected in our hospital." (PMID 37149563, 2023). "Although not statistically significant in patients with grade II or III glioma, patients with GBM in the first DKK3 tertile showed significantly greater OS and PFS rates than those in the second and third tertiles." (PMID 37149563, 2023). "Reduced expression in immortalized cells/Dickkopf-3 (REIC/Dkk-3) is a tumor suppressor gene, and expression of the REIC/Dkk-3 gene was shown to be decreased in various human tumors, including glioma." (PMID 36006934, 2022). "Some intriguing aspects of the core gene set identified in this study include the well-studied glioma-related genes ANGPT2, CD44, SPP1, STAT3, PDGRFA, and TOP2A (all up-regulated), and BRSK1, DKK3, FGFR2, MAPK9, MEF2C, and PTEN (all down-regulated)." (PMID 29352201, 2018).
glioma (continued). "In this study the expression of Dkk-3 was suppressed to undetectable levels in GBM and was lower in malignant glioma cell lines than in normal human astrocytes." (PMID 28978116, 2017). "REIC/Dkk-3 protein levels in U87ΔEGFR and GL261 glioma cells were evaluated at 36 h after treatment with Ad-CAG-REIC or Ad-SGE-REIC." (PMID 27625116, 2016). "It has been reported that DKK3 expression is essentially absent in GB and significantly reduced in glioma cell lines." (PMID 40002166, 2025). "It has also been reported that DKK3 expression is essentially absent in GB and significantly reduced in glioma cell lines." (PMID 38612910, 2024). "When the relationship between DKK3 and CSNK1A1 was calculated, a significant negative association was shown between DKK3 and CSNK1A1 in grade II glioma." (PMID 37149563, 2023). "On the other hand, in the environment of GBM, the role of DKK3, which had two contradictory roles in grade II or III glioma, may change again." (PMID 37149563, 2023). "The results showed a negative correlation between the levels of miR-92b and DKK3 in the glioma cells." (PMID 24325785, 2013). "However, when comparing the DKK3 mRNA expression levels between grade II or III glioma and GBM, we found that DKK3 expression was significantly decreased in GBM compared with grade II or III glioma." (PMID 37149563, 2023). "However, in grade III glioma, the relationship between DKK3 and CSNK1A1 was not statistically significant, and in grade IV GBM, the association between DKK3 and CSNK1A1 showed a significant positive correlation." (PMID 37149563, 2023). "In addition, DKK3 interacts with immune system-related proteins, including TCF7, THY1, and TGFβ2, and induces proliferation, angiogenesis, invasiveness, and immunosuppression of glioma cells." (PMID 35599254, 2022). "DKK3 is a critical antagonist of the Wnt/beta-catenin signaling pathway, which has been shown to be inhibited by miR-92b in neuroblastomas, but the mechanism in gliomas has not been elucidated fully." (PMID 24325785, 2013). "The actual mechanism by which DKK3 acts inhibitory on Wnt pathway activation has not been identified yet, but suppression of DKK3 increased β-catenin/T-cell factor (TCF)-dependent gene activity in mammary cells, cancerous lung cells and glioma." (PMID 19570204, 2009). "A significant positive correlation was observed between DKK3 expression and the memory B-cell fraction in the grade II or III glioma group, whereas in the GBM group, a significant negative correlation was found between DKK3 expression and the memory B-cell fraction." (PMID 37149563, 2023).
ovarian carcinoma (19 papers, 2016 to 2025). A malignant neoplasm originating from the surface ovarian epithelium. "Another study revealed that Dickkopf-3 (DKK3), a protein associated with aggressive ovarian cancer, works with HSF1 to control the behavior of cancer-associated fibroblasts (CAFs), which can promote tumor growth and invasion." (PMID 37958341, 2023). "In ovarian cancers, lower DKK3 levels are associated with an increased risk of cancer and lymphatic metastasis." (PMID 38022675, 2023). "In this study, we showed that DKK3 loss occurred in 56.1% of patients with ovarian cancer and that it was significantly associated with poor survival and chemoresistance." (PMID 35205672, 2022). "Secreted DKK3 possessed anti-tumoral properties and enhanced paclitaxel susceptibility by inhibiting the β-catenin-P-glycoprotein signaling pathway in ovarian cancer." (PMID 35205672, 2022). "This study has assessed the clinical significance of DKK3 loss and its role as a potential biotherapeutic molecule in ovarian cancer." (PMID 35205672, 2022). "As DKK3 loss was significantly associated with chemoresistance of patients with ovarian cancer, we assessed DKK3 protein level in the paclitaxel-resistant cells." (PMID 35205672, 2022). "Despite the limitations associated with the retrospective nature and small sample size of this study, this is the first report to show the clinical significance of DKK3 loss in ovarian cancer." (PMID 35205672, 2022). "An association between Dkk-3 and tumor stroma has been reported in ER-negative breast cancer, ovarian cancer, and colon cancer cells, where DKK3 gene expression is upregulated in the tumor stroma, correlating with a more aggressive tumor type." (PMID 36497305, 2022). "Therefore, secreted DKK3 exerted an anti-tumoral effect in paclitaxel-resistant ovarian cancer cells and enhanced paclitaxel susceptibility." (PMID 35205672, 2022). "DKK3 is a potential tumor suppressor, with downregulation observed in cancers such as prostate and ovarian cancer." (PMID 40231256, 2025). "In our paclitaxel-resistant ovarian cancer cells, DKK3 was downregulated and P-glycoprotein was upregulated." (PMID 35205672, 2022). "This study revealed promising therapeutic effects of secreted DKK3, which targets paclitaxel-resistant ovarian cancer." (PMID 35205672, 2022). "Previous in vitro studies have shown that the tumor suppressor potential of DKK3 is mediated via angiogenesis in ovarian cancer cell lines and via mitochondrial and Fas death receptor pathways in mucinous ovarian cancer cells." (PMID 35205672, 2022). "Our results showed that E-cadherin was upregulated in the DKK3 CM group compared to that in the control CM group, indicating that DKK3 inhibits ovarian cancer cell migration by restoring epithelial–mesenchymal transition." (PMID 35205672, 2022). "As chemoresistance is an obstacle in ovarian cancer therapy, the anti-tumoral effect of DKK3, as well as its synergistic effect with paclitaxel in paclitaxel-resistant ovarian cells, indicates the possibility of a new therapeutic strategy." (PMID 35205672, 2022). "In fact, the serum level of DKK3 in patients with ovarian cancer was found to be lower than that in normal individuals." (PMID 35205672, 2022). "This methodology has been particularly successful in ovarian cancer, where the use of a signature expression of 7 genes (including DKK-3) was able to segregate patients according to their longer or shorter survival." (PMID 34451907, 2021). "In contrast, the secreted Wnt inhibitor Dkk3 has been found to induce Fas death receptor signaling in human ovarian cancer cells, suggesting a proapoptotic role for Dkk3." (PMID 33466728, 2021). "In this regard, DKK-3 stromal expression has been associated with induction of tumor-promoting cancer-associated fibroblasts (CAF) in breast, colorectal and ovarian cancers." (PMID 34451907, 2021).
ovarian carcinoma (continued). "These analyses indicated a significant correlation between DKK3 gene expression and poor outcome in ER-negative BC patients, as well as in colon and ovarian cancer patients." (PMID 30631061, 2019). "Here we show that stromal expression of Dickkopf-3 (DKK3) is associated with aggressive breast, colorectal and ovarian cancers." (PMID 30631061, 2019). "It has been shown that Dkk-3 has a tumor-suppressive function and a pro-apoptotic effect, inducing apoptosis through mitochondrial and Fas receptor pathways in human ovarian cancer." (PMID 28978116, 2017). "The network based approach identified two 7-gene functional interaction modules (31: DCLRE1A, EXO1, KIAA0101, KIN, PCNA, POLD3, POLD2; 35: DKK3, FABP3, IRF1, AIM2, GBP1, GBP2, IRF2) that are associated with prognosis of ovarian cancer patients." (PMID 27806724, 2016). "Moreover, DKK3 exerted an anti-proliferative effect on ovarian cancer cells and reversed paclitaxel resistance by downregulating P-glycoprotein via inhibition of β-catenin." (PMID 35205672, 2022). "Here we report that DKK3 may be used as a biotherapeutic molecule to target paclitaxel-resistant ovarian cancer." (PMID 35205672, 2022). "Furthermore, DKK-3 inhibits the proliferation of ovarian cancer cells." (PMID 38201279, 2023). "Therefore, secreted DKK3 may be a potential drug to target drug-resistant cancers such as epithelial ovarian cancer." (PMID 35205672, 2022). "CircPAFAH1B2 and circUBAP2 bind to IGFBP2 and stabilize dickkopf 3(DKK3) and aryl hydrocarbon receptor (AHR) mRNAs to promote the peritoneal dissemination of ovarian cancer." (PMID 40710359, 2025). "Mechanically, Dickkopf-3 (DKK3), highly expressed in BC, CRC and ovarian cancer, is upregulated under the effect of HSF-1." (PMID 40248695, 2025). "Another study based on blood samples from patients with ovarian cancer established a negative correlation between the serum levels of DKK-3 and the amount of circulating CD133+ cells, used as a glycoprotein marker for cancer stem cells (CSCs)." (PMID 38201279, 2023). "Taken together with the results of a previous report showing the absence of DKK3 in 63% cases of 56 ovarian carcinoma tissue samples, we concluded that >50% invasive epithelial ovarian cancers lose DKK3 during carcinogenesis." (PMID 35205672, 2022). "However, the correlation of DKK3 and β-catenin-P-glycoprotein in ovarian cancer has not been reported yet." (PMID 35205672, 2022). "However, the role of DKK3 in ovarian cancer has not been evaluated." (PMID 35205672, 2022).
pancreatic cancer (19 papers, 2013 to 2026). "DKK3 inhibits the Wnt/β-catenin pathway and acts as a tumor suppressor or oncogene, when upregulated in breast, ovarian, colon, and pancreas cancers, then it is associated with poor outcomes." (PMID 40753072, 2025). "Dkk-3 has been also described as a tumor-promoting factor, especially in cancers associated with the upregulation of DKK3 expression such as in head and neck and pancreatic cancers." (PMID 36497305, 2022). "In studies using TCGA data such as ours, DKK3 was also associated with poor prognosis in head and neck squamous cell carcinoma, pancreatic cancer, and renal cancer." (PMID 35599254, 2022). "As EMT is implicated in regulating stem cell properties, we further investigated the expression of stem cell‐associated markers in DKK3‐transfected pancreatic cancer cells." (PMID 26395974, 2015). "Despite such an oncogenic role of DKK3 in non‐pancreatic cancers, we demonstrate that the role of DKK3 is more nuanced." (PMID 41147409, 2026). "Overall, our findings underscore the dual role of DKK3 in pancreatic cancer, illustrating its stage‐ and compartment‐specific expression that yields both tumor‐suppressive and oncogenic functions depending on the DKK3‐secreting cell type." (PMID 41147409, 2026). "This further supports the notion of DKK3's early role as a tumor suppressor in the progression of pancreatic cancer." (PMID 41147409, 2026). "In pancreatic cancer, the protein DKK3 is found to play a complex role: it initially slows early tumor growth but later promotes tumor aggressiveness." (PMID 41147409, 2026). "After co-culture with pancreatic cancer cells overexpressing DKK3, the glucose uptake markedly, proliferation enhanced and apoptosis inhibited in CD4+ T cells." (PMID 34391478, 2021). "For example, DKK3 suppressed tumour progression by regulating the B-catenin/EMT signalling pathway in pancreatic cancer Bxpc-3 cells." (PMID 32284738, 2020). "The high frequency of DKK3 silencing (70%) observed in ACCs is very similar to that observed in other malignancies including thyroid and pancreatic cancers." (PMID 28249601, 2017). "The forced expression of DKK3 markedly suppressed migration and the stem cell‐like phenotype of pancreatic cancer Bxpc‐3 cell in hypoxic conditions through reversing epithelial–mesenchymal transition (EMT)." (PMID 26395974, 2015). "We examined the expression of DKK3 in six human pancreatic cancer cell lines, 75 pancreatic cancer and 75 adjacent non‐cancerous tissues." (PMID 26395974, 2015). "The expression of DKK3 was significantly lower in pancreatic cancer tissues than in adjacent normal pancreas tissues." (PMID 26395974, 2015). "It is reported that DKK3 acts as a tumor suppressor in human pancreatic cancer cells via the phosphorylation of ERK." (PMID 26105053, 2015). "Meanwhile, it is reported that β‐catenin/Tcf/Lef pathway is frequently altered in pancreatic cancers 26 and DKK3 has been reported to induce changes of β‐catenin localization in cervical cancer." (PMID 26395974, 2015). "But, in DKK3‐transfected pancreatic cancer Bxpc‐3 cell, the percentage of CD133+ cells significantly fell to 1.35, 0.09 and 1.19, 0.36 respectively." (PMID 26395974, 2015). "Next, the expression levels of DKK3 protein in 75 pancreatic cancer and adjacent non‐cancerous tissues were examined by immunohistochemical (IHC) analysis." (PMID 26395974, 2015). "We also observed DKK3 potentiates the antitumour effects of gemcitabine in a subcutaneous xenograft pancreatic cancer." (PMID 26395974, 2015). "In pancreatic cancer Bxpc‐3 cell, the overexpression of DKK3 was shown to suppress EMT and migration of cell in hypoxic conditions." (PMID 26395974, 2015). "Methylation‐specific PCR analysis revealed that DKK3 methylation were detected in pancreatic cancer cell lines Aspc‐1, Bxpc‐3, CFPAC‐1, which were in agreement with the result of Western blotting." (PMID 26395974, 2015).